SMIM24 (small integral membrane protein 24)
Synonyms: C19orf77; HSPC323; MARDI
Tractability: Antibody: UniProt predicts a signal peptide or a membrane-spanning region.
Gene: Protein-coding gene on chromosome 19 (3,473,986 to 3,480,525, reverse strand). Ensembl gene ENSG00000095932.
Subcellular location: Membrane
Subcellular location (Human Protein Atlas): Nucleoplasm; Cytosol
Gene Ontology:
Cellular component: membrane
Genetic constraint (gnomAD): Loss-of-function variants: 6 observed, 9.24 expected, observed/expected ratio (o/e) 0.65, 90% interval 0.35 to 1.28. That is too few expected variants to judge how well the gene tolerates losing a copy. Missense variants: 151 observed, 157.34 expected, observed/expected ratio (o/e) 0.96, 90% interval 0.84 to 1.1. Synonymous variants: 71 observed, 65.43 expected, observed/expected ratio (o/e) 1.09, 90% interval 0.89 to 1.32.
Homologues: Orthologues: chimpanzee SMIM24 (100% identical), macaque SMIM24 (85% identical), dog SMIM24 (61% identical), rat Smim24 (57% identical), mouse Smim24 (56% identical), zebrafish smim24 (22% identical). Paralogues in human: PDZK1IP1 (22% identical).
Diseases named in the same sentence as SMIM24 in open-access papers:
SMIM24 is named in the same sentence as 13 diseases in open-access papers, as found by Europe PMC text mining. Sharing a sentence is not in itself a finding about the gene and the disease. The quoted sentences say what the papers report.
Alzheimer disease (1 paper, 2025). A progressive, neurodegenerative disease characterized by loss of function and death of nerve cells in several areas of the brain leading to loss of cognitive function such as memory and language. "With regard to SMIM24,it was considered as a kind of membrane component and mainly mentioned in Alzheimer disease." (PMID 40099255, 2025).
diabetes (1 paper, 2025). "Presently, however, no other literature exists regarding the remaining four critically differentially expressed genes, GRASP, MYZAP, PRKG1, and SMIM24, in diabetes patients." (PMID 40476695, 2025). "Several genes, including GRASP, KRT8, MYZAP, PRKG1, and SMIM24 were differentially expressed in the COVID versus no COVID and diabetes versus no diabetes subgroup analyses." (PMID 40476695, 2025).
Down syndrome (1 paper, 2025). "Another EWAS performed in drops of blood collected at birth in children with Down Syndrome (DS) showed that HOPX, SMIM24, and PPP1R10 were abnormally methylated in children with DS who developed ALL." (PMID 41226303, 2025).
Glucose intolerance (1 paper, 2021). Glucose intolerance (GI) can be defined as dysglycemia that comprises both prediabetes and diabetes. "SMIM24 (previously termed C19orf77) is a member of the small integral membrane protein family, the downregulation of which is related to steatosis, glucose intolerance, inflammation, and fibrosis in high-fat diet-, high-fat-high-cholesterol diet-, and methionine-choline-deficient diet feed mice." (PMID 34539419, 2021).
lymph node metastasis (1 paper, 2025). "Additionally, we also elucidated the correlation between SLC16A12&SMIM24 and clinical stage of ccRCC, results showed that in the patients with advanced stage including distant metastasis or lymph node metastasis, both two genes demonstrated lower expression." (PMID 40099255, 2025).
myocardial infarction (1 paper, 2021). Gross necrosis of the myocardium, as a result of interruption of the blood supply to the area, as in coronary thrombosis. "SMIM24 has an important paralog PDZK1, the downregulation of which can cause myocardial infarction-related fibrosis." (PMID 34539419, 2021).
renal carcinoma (1 paper, 2024). A carcinoma arising from the epithelium of the renal parenchyma or the renal pelvis. "The expression of FUCA1, NAT8 and SMIM24 in renal carcinoma cell lines is lower than those in renal tubular epithelial cells and suggests a better prognosis." (PMID 38517387, 2024).
tumor (2 papers, 2024 to 2025). "In contrast, the remaining two genes, SLC6A19 and SMIM24, have received significantly less attention in tumor-related research, with scant reports on their potential implications in oncology." (PMID 40099255, 2025). "The results showed that, with the exception of SMIM24, which was highly expressed in normal tissues, PLCB2, HLA-DQB2, IFNG, and XCR1 were all highly expressed in tumor tissues." (PMID 39273185, 2024).
SMIM24 also shares sentences with these, for which no sentence is quoted: acute myeloid leukemia (1 paper); blood disease (1); cancer (1); cervical adenocarcinoma (1); steatosis (1).